NRAS (NRAS proto-oncogene, GTPase)
Diseases named in the same sentence as NRAS in open-access papers (continued):
Sharing a sentence is not in itself a finding about the gene and the disease.
melanoma (continued). "Among the five melanomas harboring a rare BRAF mutation, two samples with the BRAF p.Asp594Asn showed an additional mutation in the NRAS (p.Gly12Asp) or in the KRAS (p.Gln61His) gene, previously identified in routine analysis." (PMID 31547467, 2019). "NRAS promotes leukemogenesis and NRAS/MEK/ERK signaling is a key therapeutic target in melanoma and acute myelogenous leukemia." (PMID 30953514, 2019). "Within this testing model BRAF (serine/threonine-protein kinase B-Raf) and NRAS (neuroblastoma RAS viral oncogene homolog) mutations are sequentially investigated for diagnostic purposes, as 70% of melanomas detect BRAF and NRAS as common driver mutations." (PMID 31470637, 2019). "Compound 2155–14 induces ER stress leading to the potentiation of basal autophagy and melanoma cell death in BRAF and NRAS mutated melanoma cells indicating that this can be a novel approach to a much-needed broad-spectrum melanoma therapy." (PMID 31573152, 2019). "The most used targeted therapies act on the MAPK pathway, which is mutated in NRAS and BRAF in about 25 and 60% of melanoma patients, respectively." (PMID 31013837, 2019). "Acral and mucosal subtypes of melanoma are predominant in the Japanese population, and the overall detection rates of BRAF, NRAS, and KIT mutations are approximately 30%, 12%, and 13%, respectively." (PMID 30675668, 2019). "Three-way Kruskal-Wallis analysis of the dot-plot display showed that the difference in the levels of response to SAB298 between the double-WT and NRAS-mutant melanoma cells were statistically significant, p-value = 0.002985." (PMID 31040916, 2019). "This discovery makes RAC1 the third most commonly mutated (somatic) proto-oncogene in melanoma after BRAF and NRAS." (PMID 31027363, 2019). "It was demonstrated that wild-type melanoma cell lines were more responsive to FGF2 than BRAF mutant or NRAS mutant cell lines." (PMID 31167513, 2019). "Mutations of NRAS, an upstream effector of BRAF, were found in 20% of melanoma patients and are considered to be mutually exclusive with BRAF mutations." (PMID 31877948, 2019). "Patient-derived NRAS mutated (BAK and BUL) and BRAF mutated (STU) melanoma cell lines were exposed to increasing concentrations of the MEK1/2 inhibitor trametinib (T), MBZ or a combination of T + MBZ." (PMID 31480477, 2019). "The next generation of MEK inhibitors (Trametinib, Binimetinib, and Selumetinib) have shown promising clinical efficacy even in NRAS-mutant melanoma." (PMID 31398831, 2019). "In this study we applied SynGeNet, a computational drug combination prediction method, to four subtypes of melanoma based on genomic classification of major driver events, including mutations in BRAF, NRAS, NF1, and TWT tumors." (PMID 30820351, 2019). "In conclusion, we have uncovered a range of proliferative responses to dual BRAF* and NRAS* expression in melanoma lines." (PMID 30651601, 2019). "Gains of 1q, 3p, and 17q occur more frequently in NRAS-mutant than in BRAF-mutant conjunctival melanomas." (PMID 31683701, 2019). "For instance, we identified an activating and putative resistance NRAS mutation (Q22K) in both gDNA and ctDNA in a BRAF-mutant melanoma after progression on combined BRAF and MEK inhibitors." (PMID 31795494, 2019). "We propose a restricted panel for BRAF, KRAS/NRAS, KIT, CCDN1, and CDK4 mutations in the routine diagnostic test in order to better classify the SNM subtypes of melanoma." (PMID 31581559, 2019). "This metastatic heterogeneity however, can also be present at a lower level in case of NRAS mutant melanoma." (PMID 31391014, 2019).
melanoma (continued). "Both the melanomas harbor KIT mutation in approximately 15% of the cases; BRAF or NRAS mutation is found in approximately 10–15% of acral melanoma, but these mutations are less frequent in mucosal melanoma." (PMID 30675668, 2019). "To compare our BRAF/NRAS ctDNA findings with a more established marker for disease progression in melanoma we evaluated the levels of LDH in serum (n = 2–21 time-points per patient)." (PMID 31767937, 2019). "For example, binimetinib, the most recent approved MEK1/2 inhibitor for melanoma treatment for combination therapy with a BRAF inhibitor, was able to induce at least a partial response in 20% of melanoma patients with NRAS mutations." (PMID 30987166, 2019). "It is thus possible that the prevalence of specific NRAS mutations is related, in some measure, to the activation of other RAS effector pathways to complement RAF activation for mucosal melanoma development." (PMID 31398831, 2019). "The aim of this study was to explore the molecular differences between melanoma tumor subtypes, based on BRAF and NRAS mutational status." (PMID 31076580, 2019). "Melanomas with wild-type BRAF likely have mutations in the upstream proteins of the MAPK pathway, such as NRAS or KIT." (PMID 31890008, 2019). "Several studies have compared the primary melanoma to the distant metastases with respect to BRAF and NRAS mutation statuses." (PMID 31391014, 2019). "Our further observations support the experience that BRAF and NRAS mutant melanomas behave differently during metastatic progression." (PMID 31391014, 2019). "This in silico prediction was later confirmed by analyzing clinical samples of NRAS mutant melanoma." (PMID 31681616, 2019). "Dog melanoma genes have the same mutations or aberrant expression as human melanoma genes, BRAFV600E, NRAS (Q61), PTEN, and KIT." (PMID 31569419, 2019). "Of the known melanoma driver mutations (BRAF, NRAS and NF1), only BRAF was mutated significantly more frequently in the better than in the poorer prognostic group (162/301 vs. 16/55; Fisher’s exact test, P = 0.001)." (PMID 31322504, 2019). "Conversely, the increase of the repressive histone mark, H3K9me3 was consistently observed in BRAF‐ and NRAS‐mutant melanoma cells upon exposure to magnolol and decreased upon activation of Akt." (PMID 30793515, 2019). "Other research studies have reported falling levels of circulating free DNA (ctDNA) for tumor survival-promoting mutant kinase BRAF, NRAS, and KIT alleles in melanoma patients who are undergoing immunotherapy." (PMID 30941125, 2019). "Previous studies have divided melanomas into four groups based on the driver mutation: BRAF-mutant, NRAS-mutant, NF1-mutant and triple-wild-type." (PMID 31322504, 2019). "Further, Wnt/β-catenin signaling enhances human melanoma cell migration and invasion in vivo, both in NRAS-driven mouse models of melanoma and in the neural crest of chick embryos." (PMID 30909648, 2019). "The mechanistic basis for the enhanced oncogenic activities of NRAS Q61 mutants in melanoma remains to be clearly established." (PMID 31398831, 2019). "The capability in the identification of rare and low-frequency mutations in the main genes involved in melanoma (BRAF and NRAS genes) was verified and integrated with the results deriving from other oncogenes and tumor suppressor genes." (PMID 31547467, 2019). "Since MEK1/2 are mutated in a small percentage of melanomas this further adds to the challenge of treating NRAS- and MEK1/2-mutated melanomas." (PMID 30987166, 2019). "Promising new therapies have emerged for BRAF‐mutant melanoma patients, but NRAS‐mutant (NRASMut) melanoma, like other RAS‐driven tumors, continues to have poor prognosis and limited therapeutic options." (PMID 29650805, 2018). "Treatment of the NRAS‐mutant melanoma cells showed a very different pattern of response in which vemurafenib initially suppressed growth, followed by escape and regrowth." (PMID 29112787, 2018).
melanoma (continued). "In this study, we examined POM for alterations in candidate melanoma driver genes (BRAF, NRAS, KRAS, GNA11, GNAQ) and genes implicated in UM prognosis (EIF1AX, SF3B1, BAP1)." (PMID 30558566, 2018). "BRAF and NRAS both take part in the mitogen-activate protein kinase (MAPK) pathway which significantly contributes towards melanoma development." (PMID 29492238, 2018). "Loss of ICAM-1 protein and mRNA expression was a strong prognosticator of diminished survival in BRAF/NRAS mutant melanoma." (PMID 30116025, 2018). "PTEN, the most frequently mutated gene in melanoma after BRAF and NRAS, promotes cell survival through sustained activation of the PI3K signaling pathways." (PMID 29946532, 2018). "Our findings indicate that treatment of NRAS‐mutant melanoma with BET/MEK inhibitors blocks multiple stages of the major cell cycle transitions during cell division." (PMID 29650805, 2018). "Depletion of BRD4 decreased the viability of NRAS‐mutant melanoma cells, but induced only modest apoptosis." (PMID 29650805, 2018). "In similar experiments, we found that although combining JQ‐1 with the CDK4/6 inhibitor, PD991, appeared to be effective in NRAS‐mutant melanoma (Fig EV2), this combination significantly inhibited the proliferation of non‐transformed cells." (PMID 29650805, 2018). "To assess concordance between our UACC melanoma cell lines and the CCLE melanoma cell lines, we compared NLME curve fits by subdividing the cell lines by BRAF and NRAS mutation status in both data sets." (PMID 29435161, 2018). "In 50–75% of melanomas progressing on BRAF inhibitor or combination BRAF/MEK inhibition, common resistance effectors, including BRAF copy number gains, MEK1/2 and NRAS mutations promote the reactivation of MAPK signalling." (PMID 30237495, 2018). "We selected Gamitrinib, a mitochondriotoxic small molecule, that selectively blocks mitochondrial HSP90 and exhibits broad anti-cancer activity including efficacy in BRAF-mutant melanoma, but limited activity in NRAS-mutant cells as a single agent." (PMID 29695835, 2018). "We split the candidate features into four groups: (i) clinical variables (i.e., gender, age, pretreatment, and pathologic stage); (ii) mutation status of three well-known melanoma driver genes (BRAF, NRAS, and NF1); (iii) mutation load; and (iv) ECPAcell." (PMID 30297703, 2018). "Targeted treatment of patients with NRAS mutant melanoma, remains an unsolved challenge and current therapeutic modalities only barely improve overall survival." (PMID 30405888, 2018). "We found that genetic silencing of BRD4 or pharmacological inhibition of BET/BRD proteins has mainly cytostatic effects in NRAS‐mutant melanoma cells in vitro and minimal effects in vivo." (PMID 29650805, 2018). "We next evaluated the efficacy of BET and MEK inhibitors in 3D collagen‐embedded NRAS‐mutant melanoma spheroids, as these more closely resemble the behavior of human melanoma in vivo." (PMID 29650805, 2018). "Depletion of SOD2 enhanced the ability of 6-thio-dG to induce apoptosis of NRAS-mutant melanoma cells." (PMID 29695835, 2018). "We noted that TCF19 is expressed in NRAS‐mutant melanoma cells and in melanocytes, albeit at lower levels." (PMID 29650805, 2018). "We followed up on this discovery in an attempt to improving the stratification of NRAS mutant melanoma patients that are most likely to respond." (PMID 30405888, 2018). "In this particular case, we suggest incorporating the NRAS mutation status, but omitting the BRAF mutation status, in fitting NLME curves for Topotecan in melanoma cell lines." (PMID 29435161, 2018). "We show that BET proteins are overexpressed in NRAS‐mutant melanoma and that high levels of the BET family member BRD4 are associated with poor patient survival." (PMID 29650805, 2018).
melanoma (continued). "Insufficient cases were available to assess ITGAV transcripts as a biomarker in wildtype NRAS/BRAF melanoma." (PMID 30116025, 2018). "Meantime, another study showed that canine melanoma possesses rare mutations in the B-Raf (BRAF) and N-ras (NRAS) proto-oncogenes; however, they present similar gene expression changes to human melanoma within the same downstream activation pathways." (PMID 30459395, 2018). "Activation of the effector caspase‐7 was observed in all NRAS‐mutant melanoma cell lines following co‐inhibition of BET and MEK." (PMID 29650805, 2018). "Yet, the ability of 17-AAG to inhibit MAP kinase activity and cell proliferation was retained in NRAS mutant melanoma cell lines." (PMID 29481571, 2018). "We report that BET proteins are overexpressed in NRAS‐mutant melanoma, and that these tumors are dependent on the BET family member, BRD4." (PMID 29650805, 2018). "Second, it is important to consider that the database derived observation that CDK4 is a MEK co-extinction target mimicking NRAS abrogation is, at least in part, affected by the frequent cell cycle alterations in melanoma (models) in general." (PMID 30405888, 2018). "We next sought to clarify the requirement for the catalytic activity of TERT for the pro-survival function of this protein in NRAS-mutant melanoma." (PMID 29695835, 2018). "The authors therefore combined BRD4 inhibition with targeting other deregulated signaling molecules in NRAS‐mutant melanoma cells, such as MEK, PI3K, and CDK4/6." (PMID 29661909, 2018). "Depletion of TCF19 with two different shRNA constructs led to an increase of cells in G2/M followed by apoptosis of NRAS‐mutant melanoma cells." (PMID 29650805, 2018). "PLX4032, (vemurafenib) an ATP-competitive RAF inhibitor, inhibits ERK signaling and cell proliferation in BRAFV600E melanomas, but enhances the signaling in BRAFWT cells with mutated NRAS." (PMID 29481571, 2018). "Our results raise the possibility that the synergistic repression of the transcription factor TCF19 triggered by concomitant BET and MEK inhibition renders NRAS‐mutant melanoma cells more vulnerable to apoptosis." (PMID 29650805, 2018). "NEK9 and CDK16 were chosen for further study based upon their potent inhibition by dabrafenib in in vitro kinase assays, and by preliminary siRNA experiments in which their silencing inhibited the growth of NRAS‐mutant melanoma cells." (PMID 29112787, 2018). "NRAS‐mutant melanoma is an archetype of therapeutic challenges in the field, which we used to test drug combinations to avert drug resistance." (PMID 29650805, 2018). "Studies using the biguanides metformin and phenformin, both indirect AMPK activators, showed minimal effects on ERK dephosphorylation in both BRAF wild type and BRAFV600E mutant, as well as NRAS mutant melanomas." (PMID 30651927, 2018). "NRAS is an established oncogene involved in the pathogenesis of other cancer types, including leukemia and melanoma." (PMID 29682098, 2018). "Pre-treatment of NRAS-mutant melanoma spheroids with 6-thio-dG markedly potentiated the effect of Gamitrinib, and induced apoptosis of 3D melanoma spheroids." (PMID 29695835, 2018). "Then we examined BRaf and NRas status in DOT1L-null mouse melanomas and found that BRaf (V637, homolog to human BRaf V600) mutations are frequently observed in melanomas from Dot1l-null transgenic mice (n = 4/7)." (PMID 29343685, 2018). "Together, our results indicate that therapeutic approaches exploiting melanoma cell addiction to TERT, and combating the ability of NRAS-mutant melanoma to offset oxidative stress, would render cancer cells vulnerable to drug-induced cell death." (PMID 29695835, 2018). "Combining 6-thio-dG with the mitochondrial inhibitor Gamitrinib attenuated this adaptive response and more effectively suppressed NRAS-mutant melanoma." (PMID 29695835, 2018).
melanoma (continued). "We investigated the consequences of NRAS blockade in NRAS-mutant melanoma and show that decreased expression of the telomerase catalytic subunit, TERT, is a major consequence." (PMID 29695835, 2018). "To better understand the mechanism whereby MEK and BET inhibitors cooperate to inhibit the growth of NRAS‐mutant melanoma, we performed RNA‐sequencing and proteomic analysis of cells treated with single‐agent JQ‐1, PD901, or the combination of both drugs." (PMID 29650805, 2018). "Similar survival trends were also observed for this molecular phenotype using the TCGA-SKCM dataset mRNA transcript level information of Stage III NRAS/BRAF melanoma specimens." (PMID 30116025, 2018). "Pan-RAF and MEK double treatment proved to be an effective therapeutic strategy in vitro in NRAS mutant melanomas, when RAS/RAF/MEK/ERK pathway is activated and dependence of proliferation and survival on this pathway is demonstrable." (PMID 29739364, 2018). "SK-Mel-2 melanoma cells have been reported to contain either an NRASQ61R or a KRASQ61R mutation, but sequencing of the amplified exons 3 of NRAS and KRAS in the cells used in our experiments confirmed that the mutation is NRASQ61R, not KRASQ61R." (PMID 29481571, 2018). "Combining BET and MEK inhibitors synergistically curbed the growth of NRAS‐mutant melanoma and prolonged the survival of mice bearing tumors refractory to MAPK inhibitors and immunotherapy." (PMID 29650805, 2018). "Cobimetinib is a highly selective MEK1 inhibitor studied as a targeted therapy in BRAF and NRAS mutant melanoma, and it has been tested in preclinical studies in NRAS mutant AML." (PMID 29857559, 2018). "In NRAS-mutant melanoma models, it has been proposed that MEK inhibitor-dependent induction of apoptosis is countered by proliferative responses within the tumor." (PMID 30167080, 2018). "To determine the dependency of NRAS-mutant melanomas on TERT, we evaluated the effect of TERT silencing in these cells." (PMID 29695835, 2018). "Following this lead, they tested JQ1, a BET inhibitor and anticancer drug, in NRAS‐mutant melanoma cells and found that it reduces their viability—the degree of reduction correlated with the protein levels of BRD4 reversely." (PMID 29661909, 2018). "Alternatively, activation of wild-type BRAF (BRAFWT) and CRAF can occur through activating mutations in NRAS, or KIT, or and through NF1 deletion, which occur in approximately 20% of melanomas." (PMID 29481571, 2018). "MLPA was conducted to detect chromosomal alterations and Sanger sequencing used to identify point mutations in candidate melanoma driver genes (BRAF, NRAS, KRAS, GNA11, GNAQ), and other genes implicated in melanoma prognosis (EIF1AX, SF3B1)." (PMID 30558566, 2018). "Novel strategies and new druggable downstream targets of NRAS are therefore needed to improve the precision and efficiency of anti‐NRAS‐mutant melanoma therapies." (PMID 29661909, 2018). "Briefly, 58/124 (46.8%) primary melanomas and 70/150 (46.7%) metastatic tissues presented mutations in BRAF gene, whereas NRAS mutations were found in 19/124 (15.3%) primary tumors and 24/150 (16.0%) melanoma metastases." (PMID 29492214, 2018). "Consistent with previous reports indicating that the RAS/MEK signaling pathway regulates TERT expression, treatment of NRAS-mutant melanoma cells with the MEK inhibitor trametinib downregulated TERT mRNA levels." (PMID 29695835, 2018). "Alterations in BRAF, NRAS, and NF1 define the canonical genetic subtypes of melanoma, yet each of these oncogenic mutations is insufficient to drive tumorigenesis." (PMID 29875996, 2018). "In one study of 318 melanoma specimens, mutations in BRAF or NRAS were detected in 166 (52%) and 88 (28%), respectively." (PMID 30113761, 2018). "Decreased RB phosphorylation and increased p27 expression were also observed in other NRAS‐mutant melanoma and KRAS‐mutant pancreatic carcinoma cells." (PMID 29112787, 2018).